NF2 (NF2, moesin-ezrin-radixin like (MERLIN) tumor suppressor)
Diseases named in the same sentence as NF2 in open-access papers (continued):
Sharing a sentence is not in itself a finding about the gene and the disease.
meningioma (continued). "FAK and mTOR inhibitors are a promising advancement in targeted meningioma therapy, in individuals with NF2 associated or NF2 related meningioma." (PMID 37860270, 2023). "Coding for Merlin, NF2 is considered the most probable meningioma-associated gene located in this region and is found in 50-60% of meningioma." (PMID 37860270, 2023). "Postoperatively, NF2 mutant tumors are associated with higher rates of recurrence and undergo post-operative radiotherapy more frequently than non-NF2 mutant meningiomas." (PMID 37010677, 2023). "The presence of NF2 mutations is the basis for the classification of meningiomas into a subtype that has NF2 gene alterations and a subtype associated with non-NF2 somatic mutations." (PMID 38001599, 2023). "Meningiomas with mutations in non-NF2 genes are less common, more heterogeneous, and often result in different tumor phenotypes." (PMID 38001599, 2023). "While genomic markers of meningiomas, like NF2 mutations, have been explored, the search for other classes of biomarkers is in progress." (PMID 38001599, 2023). "Most meningiomas with these non-NF2 mutations tended to be more benign, of lower WHO grade, and associated with less chromosomal abnormalities." (PMID 36840836, 2023). "Since the discovery of non-NF2 driver mutations in meningiomas, other prognostically important genomic alterations have since been uncovered." (PMID 36840836, 2023). "According to the latest two reports, one reasonable explanation for this is that NF2 predisposes patients to the development of meningiomas that then have independent growth rates or clinical outcomes." (PMID 37752594, 2023). "Sphenoid wing meningiomas harboring NF2 mutations tend to demonstrate bony invasion with frank tumor, while TRAF7-mutant tumors are associated with hyperostosis." (PMID 37010677, 2023). "In fact, 60% of meningiomas have been characterized by an NF2 gene deficiency caused by promoter methylation, epigenetic inactivation, monosomy of chromosome 22, or a somatic mutation." (PMID 38001599, 2023). "The most frequent coding changes identified in non-NF2 meningiomas were missense mutations in TNF Receptor Associated Factor 7 (TRAF7), Kruppel-like factor 4 (KLF4), and RAC(Rho family)-alpha serine/threonine-protein kinase 1 (AKT1)." (PMID 36937440, 2023). "We used RNA sequencing (RNA-seq) to determine whole transcriptome profiles of twenty meningiomas with genomic alterations including NF2 inactivation, loss of chr1p, and missense mutations in TRAF7, AKT1 and KLF4." (PMID 36937440, 2023). "Type C meningiomas, characterized by NF2 loss and genomic instability, were proposed to be deficient in the repressive dimerization partner, RB-like, E2F and multi-vulval class B (DREAM) complex, a master regulator of gene expression." (PMID 36937440, 2023). "NF2 is associated with the development of schwannomas at multiple sites, including the bilateral vestibular portion and meningiomas." (PMID 37629179, 2023). "Patients with NF2-related schwannomatosis develop different types of tumors, e.g., meningiomas, ependymomas or—as a hallmark tumor—VS, due to the loss of the tumor suppressor protein merlin." (PMID 37627117, 2023). "Broadly, they can be dichotomized as NF2 mutation and non-NF2-mutated meningioma due to the high prevalence of NF2 mutations." (PMID 38023177, 2023). "This association and progression of meningiomas in NF2 patients is linked with the NF2 gene mutation, as studies have shown that NF2 serves as a tumor suppressor in meningioma tumorigenesis." (PMID 37675219, 2023). "NGS has led to the identification of novel driver gene mutations in meningioma in addition to NF2, including SMO, PI3KCA, TRAF7, KLF4, AKT1, POLR2A, and SMARCE1." (PMID 38066633, 2023). "In human schwannomas and meningiomas, loss of NF2 leads to activation of PI3K/AKT/mTOR and thereby inhibits cancer cell proliferation." (PMID 37351538, 2023).
meningioma (continued). "We observed somatic mutations or fusions in NF2 in 41% (7/17) of meningiomas, 5% (3/60) of ependymomas, and 25% (3/12) of schwannomas, as well as rare fusions in ERBB4, YAP1, and/or QKI in 10% (6/60) of ependymomas." (PMID 37492101, 2023). "In 2013, two separate landmark studies utilized whole genome and whole exome sequencing to uncover novel mutations in non-NF2 meningiomas including TRAF7 (TNF receptor associated factor 7), KLF4 (Krüppel-like factor 4), AKT1, and SMO (Smoothened)." (PMID 36840836, 2023). "Important driver mutations specifically associated with meningioma pathology (including NF2, TRAF7, SMO, PIK3C2B and AKT1) that were identified in the tissues were consistently found in spheroids." (PMID 38102708, 2023). "NF2 somatic mutations have also been observed in sporadic tumors related to NF2 cancer syndrome such as meningioma, vestibular schwannoma, and other malignancies, albeit at low frequency, including breast, liver, and kidney cancers." (PMID 37180489, 2023). "Meningiomas are the most common primary intracranial tumors and are associated with inactivation of the tumor suppressor NF2/Merlin, but one-third of meningiomas retain Merlin expression and typically have favorable clinical outcomes." (PMID 36993679, 2023). "NF2 is the most commonly involved gene, with up to 60% of sporadic meningiomas exhibiting biallelic mutation or loss of the NF2 tumour suppressor gene on chromosome 22." (PMID 36882706, 2023). "Earlier studies demonstrated that up to 60% of sporadic meningiomas exhibit biallelic Neurofibromin 2 (NF2) gene inactivation due to chromosome 22 monosomy with concurrent NF2 point mutations (NF2 meningiomas/tumors)." (PMID 36937440, 2023). "NF2 is a mutated gene in brain tumors, and deletion of NF2 predisposes meningiomas to ferroptosis, and E-cadherin is negatively associated with ferroptosis." (PMID 36910646, 2023). "Recent studies have indicated that YAP1 activation is frequently associated with the loss of function of the potent tumor suppressor NF2/Merlin, which drives tumor growth, invasion, and resistance to apoptosis in various tumors, including meningioma." (PMID 37628996, 2023). "Other non-NF2 mutational signatures that are prevalent in meningioma include TRAF7, AKT1, POLR2A, PIK3CA, KLF4, SMARCE1, and BAP1." (PMID 37887327, 2023). "As another potential target, focal adhesion kinase (FAK) inhibition has been shown to exert antitumoral activity in in vitro meningioma models with NF2 loss." (PMID 36181606, 2023). "TRAF7 mutations occur in ~ 25% of meningiomas and seem to be mutually exclusive with NF2 mutations according to a genomic landmark study of 300 meningiomas." (PMID 36181606, 2023). "Conversely, although NF2 mutations are frequently observed in spontaneous schwannomas and meningiomas, these mutations occur less frequently in other sporadic solid tumors, such as breast and colorectal cancers." (PMID 37730636, 2023). "MG2 or NF2-wildtype meningiomas likely belong to the same group as the MI and MenG A groups, comprised of benign-behaving meningiomas with non-NF2 driver mutations." (PMID 36840836, 2023). "Mutations at the amino-terminal domain of the NF2 are associated with more meningiomas, especially in the intracranial space." (PMID 37217995, 2023). "This review summarizes the known genetic and epigenetic aberrations involved in meningiomas, with a focus on neurofibromatosis type 2 (NF2) and non-NF2 mutations." (PMID 38001599, 2023). "Conversely, patients with neurofibromatosis type 2 carrying germline mutations in NF2 have a significantly higher risk for meningioma in their lifetime and even during childhood." (PMID 36181606, 2023). "Loss-of-function mutations in NF2 lead to tumorigenesis, including schwannoma, meningioma, and ependymoma." (PMID 36746934, 2023). "Especially the rare genetic disorder neurofibromatosis type 2 (Nf2) at q22 predisposes to meningiomas of which approximately 50% display alteration of the tumor suppressor." (PMID 37898750, 2023).
meningioma (continued). "Meanwhile, for NF2-mutated meningiomas, a phase-II study of GSK2256098, another FAK inhibitor, has been shown to be well tolerated, resulting in an improved progression-free survival rate." (PMID 37180489, 2023). "Three children (30%) had evidence of associated type 2 neurofibromatosis (NF2), and all of them had multiple meningiomas." (PMID 37760417, 2023). "Inactivating alterations in NF2 with subsequent chromosome 22 loss is frequently described among meningiomas." (PMID 36980535, 2023). "YAP1 is a transcriptional coactivator of cell growth that is regulated by the Hippo signaling pathway and is especially associated with pediatric Nf2 wild-type meningiomas." (PMID 37898750, 2023). "The meningioma was also sequenced and found to have an NF2 p.Glu34fs frameshift variant (predicted to encode a premature stop of translation) and loss of chromosome 22q." (PMID 36980535, 2023). "NF2 gene mutations have been used as potential meningioma biomarkers, but proteomic-based biomarkers are better suited to accommodate meningioma diversity." (PMID 38001599, 2023). "Overexpression of the platelet-derived growth factor (PDGF) in arachnoïdal cells using the RCAS-TVA system leads to meningioma development independently of NF2 mutations." (PMID 38001599, 2023). "We identified 18 SCNAs that were statistically mutually exclusive (at a 5% false discovery rate [FDR]) with losses of chromosome 22q that overlap with NF2 (22q-loss), a well-established driver of meningiomas." (PMID 37805627, 2023). "CNV analysis showed that 22q loss was found in 69% (64.3% of NF2 patients’, 73.3% of sporadic NF2-altered meningiomas, p = 0.7)." (PMID 37752594, 2023). "One outcome of such advances was the association between meningioma formation and NF2 gene inactivation." (PMID 38001599, 2023). "The accumulation of copy number losses, including 1p, 6p/q, 10q, 14q, and 18p/q, and less frequently 2p/q, 3p, 4p/q, 7p, 8p/q, and 9p, compatible with instability, is restricted to NF2 mutated meningioma." (PMID 36230612, 2022). "Previous studies showed that more than 60% of sporadic meningioma patients harbored somatic mutation, epigenetic inactivation, or allele loss of NF2 on chr22q." (PMID 36267986, 2022). "The NF2 gene was first implicated in meningiomas after it was found that its inactivation resulted in the genetic tumor predisposition syndrome of neurofibromatosis type 2." (PMID 36267986, 2022). "NF2-mutated meningiomas demonstrate larger volumes, fibrous or atypical histology, male predominance, and preferentially occur along the cerebral convexities posterior to the coronal suture." (PMID 34846640, 2022). "Somatic mutations of NF2 are also observed in spontaneous schwannomas, meningiomas, mesothelioma and renal cell cancer." (PMID 36523977, 2022). "Since 40-60% of sporadic meningiomas have a loss of NF2 expression, meningiomas can be molecularly categorized into NF2 mutants and non-NF2 mutants, with the latter predominantly comprised of TRAF7, KLF4, AKT1, SMO, and P13K mutations." (PMID 35712492, 2022). "SMO mutations which activate Hedgehog signaling were identified in 5% of non-NF2 mutant meningiomas and NF2 and/or chromosome 22 loss were more likely to be atypical meningiomas." (PMID 36033542, 2022). "A FAK inhibitor (GSK2256098) was identified to significantly improve the survival rates of patients with recurrent or progressive NF2-mutated meningiomas (NCT02933736)." (PMID 35712491, 2022). "Molecular genetic studies have revealed that NF2 gene variants and 22q loss occur in approximately 40–60% and 60–70% of sporadic meningiomas, respectively." (PMID 35804955, 2022). "The pathological diagnosis after all his resections remained WHO grade 2 meningioma, with sequencing after his second surgery revealing only a NF2 mutation." (PMID 35402234, 2022). "Loss of NF2 function is commonly detected in many cancers including malignant mesothelioma, meningioma and schwannoma." (PMID 36523977, 2022).
meningioma (continued). "We found that NF2 alteration/22q loss is associated with recurrence in WHO grade 1 sphenoid wing meningiomas, as well as some radiological findings." (PMID 35804955, 2022). "The loss of merlin expression is characteristic of all NF2-associated meningiomas and nearly half of sporadic cases." (PMID 36713513, 2022). "According to the CNS WHO classification, more than 30% of NF2-mutated meningiomas are grade 2–3 and recur more frequently than the others." (PMID 36230612, 2022). "As a result of these findings, a phase II/III trial of REC-2282 in NF2 patients with meningiomas, as well as sporadic meningiomas with NF2 mutations has begun (NCT05130866)." (PMID 36033542, 2022). "The duration of recurrence was significantly shorter for meningiomas with NF2 alteration/22q loss (p = 0.0007) even if gross-total resection was achieved." (PMID 35804955, 2022). "Due to the expertise in skull base surgery and neurofibromatosis type 2, the cohort includes more meningiomas of the skull base as well as recurrent and NF2 associated tumors." (PMID 33899156, 2022). "The initial loss of chromosome 22q in meningioma tumorigenesis has long been established as an early chromosomal event linked to both NF2 mutated and non-NF2 mutated tumors." (PMID 36686824, 2022). "Numerous chromosomal regions appear to be recurrently affected by CNVs in meningiomas, most commonly loss of chromosome arm 22q, which contains the NF2 locus." (PMID 36315366, 2022). "The two meningiomas, one frontal and one occipital, harbored a somatic NF2 mutation along with deletions affecting chromosomes 1p, 2 and 22, suggesting a monoclonal origin." (PMID 35568945, 2022). "The main predisposing factors for meningioma development are inactivation of the NF2 gene and exposure to ionizing radiation, which can be causative for multiple neoplasms." (PMID 35163107, 2022). "As NF2 mutation was predominantly the commonest mutation in meningioma, we simplified the analyses by categorizing the meningioma as NF2 or non-NF2." (PMID 35570314, 2022). "In descending order of frequency, the second type of tumor in patients with NF2 gene mutations are meningiomas, the intracranial location being more common and with earlier onset than those within the spine." (PMID 35053664, 2022). "Aggressive NF2-mutated meningiomas acquire chromosomal instability or co-mutation in another tumor suppressor gene, SMARCB1." (PMID 34846640, 2022). "TRAF7 is also one of four genes including KLF4, AKT1, and SMO, likely to be mutated in non-NF2 mutated meningiomas found at the skull base." (PMID 36686824, 2022). "The group with highest recurrence rate (ED2) was highly enriched in mutations of NF2, a gene whose loss of function is highly associated with atypical meningioma." (PMID 35440040, 2022). "The genomic profile of a large cohort of meningiomas has identified alteration in the genes encoding for NF2, SMARCB1, SMARCE1, TRAF7, KLF4, POLR2A, BAP1, and members of the PI3K and Hedgehog pathways." (PMID 35706426, 2022). "Studies have found predominantly immunosuppressive type macrophages in AKT1 mutated meningiomas, while NF2 gene mutated tumors have high levels of immune active macrophages." (PMID 36033542, 2022). "NF2:SMARCB1 co-mutated meningiomas have been shown to have a higher proliferative index, are part of the pathway to aggressiveness and higher grade in meningiomas and seem to benefit from greater EOR with regards to prevention of recurrence." (PMID 35568945, 2022). "A notable exception to this is NF2, which is mutated in the hereditary condition neurofibromatosis type 2, which causes development of benign schwannoma, meningiomas and ependymomas." (PMID 35119068, 2022). "In contrast, clumps associated with mutations in NF2 (neurofibromin 2), a common driver of meningioma, scored lower in the XCVATR clump analysis." (PMID 36539717, 2022).
meningioma (continued). "The gene most frequently altered is the tumor suppressor merlin (NF2); a mutation in this gene is present in approximately 45% of meningiomas." (PMID 36514795, 2022). "Meningiomas can be induced in GEMMs overexpressing PDGFB in a context of loss of function of Nf2, Cdkn2ab or p16Ink4a or over-expressing only SmoM2 PGDS+ arachnoid cells." (PMID 35706426, 2022). "Two phase II clinical trials are currently underway to test FAK inhibitor GSK2256098 and AZD2014 in patients with NF2-mutated meningiomas and NF2 patients with symptomatic meningiomas respectively." (PMID 36686824, 2022). "Together, these findings suggest that NF2 alteration/22q loss is associated with recurrence in WHO grade 1 sphenoid wing meningiomas." (PMID 35804955, 2022). "In human, germline or somatic mutations in one allele of NF2 results in the disease neurofibromatosis type 2, which is associated with schwannomas, meningiomas, and ependymomas." (PMID 36551696, 2022). "The most frequent alteration in meningioma is the loss of the neurofibromin 2 (NF2) gene on chromosome 22." (PMID 35565385, 2022). "Exome sequencing and copy number analysis of our meningioma/dura pairs identified 5 tumors with NF2 alterations (3 mutations and 2 deletions) and 7 NF2 wildtype meningiomas." (PMID 35769412, 2022). "In a study of 88 sporadic meningiomas, 49% exhibited allelic loss of chromosome 22, 24% had NF2 somatic mutations and 26% had aberrant NF2 promoter methylation." (PMID 36267986, 2022). "The CNV profiles showed a homozygous loss of CDKN2A/B, loss of PTEN, and/or NF2 genes in 0%, 0%, and 50% of grade 1 meningiomas; 0%, 42%, and 91% of grade 2 meningiomas; and 40%,100%, and 100% of grade 3 meningiomas, respectively." (PMID 36551712, 2022). "Among the genetic syndromes associated with predisposition to CNS tumors, neurofibromatosis type 2 (NF2) is the most strongly associated with meningioma risk." (PMID 36201196, 2022). "Intriguingly, between 20% and 40% of pediatric patients with meningiomas harbor the NF2 mutation, and up to 1% of all meningiomas are correlated with this syndrome." (PMID 35053664, 2022). "While one of the meningiomas was located along the convexity, the other localized to the skull base, a region usually associated with non-NF2 mutated meningiomas." (PMID 35568945, 2022). "These included the earliest finding of chromosome 22q deletion, which causes the loss of the tumor suppressor gene NF2, the inactivation of which was observed in about half of the meningiomas studied." (PMID 36551712, 2022). "Most somatic NF2 mutations are in solitary, sporadic meningiomas, however, they can occur in radiation-induced and multiple meningiomas." (PMID 34846640, 2022). "Sporadic mutations in the NF2 gene on chromosome 22 are implicated in 40 to 60% of meningioma patients, while 50 to 75% of patients with germline mutations develop meningiomas." (PMID 36686824, 2022). "SMARCB1 R386H mutation was reported in 2.4% of meningiomas, mostly in association with NF2 mutations (73.6%)." (PMID 35049691, 2022). "FOXM1 has also been implicated as one of three genes upregulated in primary atypical meningiomas, which have also been found to demonstrate NF2 loss, genomic instability, mutations in SMARCB1, and a hypermethylated phenotype." (PMID 36686824, 2022). "On the other hand, the most common tumor suppressor gene effected in meningiomas is the NF2 gene, encoding Merlin." (PMID 35216092, 2022). "A study including 775 samples revealed that the loss of NF2 or co-occurrence with recurrent SMARCB1 mutations frequently occurs in atypical meningiomas." (PMID 35712491, 2022). "A subset of NF2 mutant meningiomas exhibit recurrent mutations in SMARCB1 (most frequently SMARCB1R368H and SMARCB1R377H), which, like NF2 is located on chromosome 22q." (PMID 36497370, 2022).